NCOR1 (nuclear receptor corepressor 1)
Diseases named in the same sentence as NCOR1 in open-access papers (continued):
Sharing a sentence is not in itself a finding about the gene and the disease.
infection (5 papers, 2008 to 2023). The state of being infected such as from the introduction of a foreign agent such as serum, vaccine, antigenic substance or organism. "We found that TFEB expression was reduced at an early point of infection in NCoR1-deficient conditions, indicating a crucial role of NCoR1 in TFEB functionality." (PMID 37590294, 2023). "We further assessed the NCoR1 protein levels in Mtb-infected mo-MΦ using western blotting and found its peak expression at 12 h post infection, which goes down at later time points." (PMID 37590294, 2023). "We found decreased phospho-TFEB and increased TFEB with LC3-II levels in mTOR inhibited condition of NCoR1 KD mo-MΦ at 2 h and 24 h post H37Rv infection." (PMID 37590294, 2023). "Hypoxic molecule HIF-1α (stabilisation has antimicrobial activity) was also found to be decreased in the NCoR1 KD condition at 24 h post infection." (PMID 37590294, 2023). "Overall, these results depicted that NCoR1 expression was significantly increased during the early course of H37Rv infection, which goes down after 24 h, hinting towards an important role in host responses against Mtb infection." (PMID 37590294, 2023). "Similar findings were made in Mtb-infected PBMCs, where early infection showed increased NCoR1 expression, which thereafter decreased at 24 h." (PMID 37590294, 2023). "To gain a global insight into the mechanistic aspect, we performed RNA-seq analysis of Mtb-infected control and NCoR1 KD mo-MΦ at 2 h and 24 h post infection." (PMID 37590294, 2023). "Comparable results are seen in the Mtb-infected PBMCs, wherein the NCoR1 expression is elevated at the beginning of infection and then reduced after 24 h." (PMID 38138088, 2023). "Antimycin-A treatment reduced the ATP levels and a subsequent reduction in infection levels were observed in NCoR1 KD mo-MΦ upon M. smegmatis infection." (PMID 37590294, 2023). "To ascertain the role of TFEB in compromised autophagy and lysosomal biogenesis, we overexpressed the flag-tagged TFEB in NCoR1 KD mo-MΦ followed by H37Rv infection for 24 h." (PMID 37590294, 2023). "The MFI also depicted a significantly increased shift for H37Rv infection in NCoR1 KD cDC1 as compared to controls." (PMID 37590294, 2023). "Though cDC1 showed early induction of NCoR1 at 6 h in western blot analysis post infection, the trend was similar to the results observed in macrophages." (PMID 37590294, 2023). "The significance of NCoR1 for the regulation of host defense against infection is highlighted by its increased expression in myeloid cells during the initial stages of Mtb infection." (PMID 38138088, 2023). "We also found that NCOR1 (nuclear receptor corepressor 1) expression was sensitive only to Mut-2 infection." (PMID 29207503, 2017). "NCoR1 depletion at the protein level was confirmed upon H37Rv infection." (PMID 37590294, 2023). "We also quantified phagocytosis rate kinetics to observe infection difference at early time points between control and NCoR1 KD cells using yellow-green latex beads and M. smegmatis infection at 10 min, 30 min, and 60 min time points using flow cytometry and CFU assay." (PMID 37590294, 2023). "We observed dynamic changes in the NCOR1 transcript levels, where its expression was found to be significantly increased during early time points till 24 h and then it went down at 48 h post infection." (PMID 37590294, 2023). "To assess the impact of NCoR1 depletion on Mtb load, we infected the control and NCoR1 KD mo-MΦ by pathogenic strain of Mycobacterium tuberculosis, i.e., H37Rv and nonpathogenic laboratory strain M. smegmatis to quantify the bacterial load using CFU assay at 24 h post infection." (PMID 37590294, 2023). "In addition, we confirmed these results by flow cytometry using mCherry-tagged H37Rv or M. smegmatis, where we observed similar and significantly increased percent infection along with their respective mean fluorescence intensity (MFI) shifts for H37Rv or M. smegmatis in NCoR1 KD mo-MΦ." (PMID 37590294, 2023).
infection (continued). "We found that NCoR1 KD mo-MΦ showed significantly decreased Beclin1 and ATG12-ATG5 protein levels upon H37Rv infection." (PMID 37590294, 2023).
metabolic disease (5 papers, 2016 to 2024). A congenital disorder (due to inherited enzyme abnormality) or acquired (due to failure of a metabolically important organ) disorder resulting from an abnormal metabolic process. "As such, knockout of NCoR1 in mice results in increased metabolic homeostasis and improved insulin response, two hallmarks linked to a lower prevalence of metabolic disorders." (PMID 37059182, 2023). "In conclusion, HDAC3, NCoR1, and NCoR2 play a major role in regulating metabolism and have been implicated in several metabolic diseases." (PMID 37674539, 2023). "Further studies are needed to thoroughly understand the mechanisms through which HDAC3, and NCoR1/2 govern metabolic processes and the implications for treating metabolic diseases." (PMID 37674539, 2023). "Understanding the specific mechanisms by which HDAC3 and NCoR1 interact with lipid metabolism genes is essential for unraveling their roles in liver function and exploring potential therapeutic targets for metabolic diseases related to lipid metabolism." (PMID 37674539, 2023). "A comprehensive identification of target genes and pathways regulated by HDAC3 and NCoR1 in the context of inflammation and metabolic diseases is essential for the drug development." (PMID 37674539, 2023). "In conclusion, despite significant progress in understanding how HDAC3 and NCoR1 control inflammation in metabolic disorders, there are still various areas that researchers can explore to deepen our knowledge and identify potential therapeutic strategies." (PMID 37674539, 2023). "We describe the relationship between the corepressor NCoR1 and its E3 ubiquitin ligase Siah2 and the potential of manipulating their mutual regulation to treat metabolic diseases." (PMID 26832397, 2016). "As such, the NCoR1–PABPC4 interface might be a new road to the treatment of metabolic diseases." (PMID 37059182, 2023). "Therefore, this new metabolic interface mediated by a physical interaction between PABPC4 and NCoR1 may provide new insights for targeting metabolic disorders." (PMID 37059182, 2023).
cardiovascular diseases (2 papers, 2023). "Nuclear receptor corepressor 1 (NCOR1) plays an important role in metabolic and cardiovascular diseases by regulating the function of macrophages." (PMID 38030614, 2023).
bacterial infection (1 paper, 2023). "We therefore considered whether NCoR1 KD mo-MΦ has a similar kind of perturbation at cellular energy levels upon bacterial infection or not." (PMID 37590294, 2023).
NCOR1 also shares sentences with these, for which no sentence is quoted: acute myeloid leukemia (5 papers); esophageal cancer (3); Iron deficiency anemia (3); medulloblastoma (3); Glucose intolerance (2); myeloid leukemia (2); ovarian carcinoma (2); retinoblastoma (2); acute leukemia (1); acute lymphoid leukaemia (1); acute monocytic leukemia (1); age-related macular degeneration (1); Allergy (1); Alzheimer disease (1); Arthritis (1); autoimmune thyroid disease (1); benign adenoma (1); bone tumor (1); Central hypothyroidism (1); colorectal adenocarcinoma (1); coronary artery disease (1); embryonal rhabdomyosarcoma (1); endometrial cancer (1); endometriosis (1); Fanconi anemia complementation group E (1); fibrosis (1); graft versus host disease (1); granulosa cell tumors of the ovary (1); hearing loss (1); hematopoietic cancers (1).
A further 23 diseases each share a sentence with NCOR1 in 1 paper.